JAK2 (Janus kinase 2)
Diseases named in the same sentence as JAK2 in open-access papers (continued):
Sharing a sentence is not in itself a finding about the gene and the disease.
lung cancer (continued). "The ERK1/2 and JAK2 signaling pathways participate in the progression and metastasis of lung cancer, and are attractive therapeutic targets for NSCLC30–32." (PMID 30038287, 2018). "Further mechanistic studies demonstrated that CAFs enhanced the metastatic potential of lung cancer cells by secreting IL-6, subsequently activating of JAK2/STAT3 signaling pathway." (PMID 29100297, 2017). "The wound healing results showed that the blockade of JAK2/STAT3 signaling effectively reversed the enhanced abilities of migration of lung cancer cells by CAF-CM." (PMID 29100297, 2017). "Collectively, TM4SF4-derived signaling pathways including GSK3β/β-catenin and JAK2(or FAK)/STAT3 appear to be focused on the secretion level of OPN and thus strengthen EMT-associated CSC-like properties in lung cancer cells." (PMID 29254164, 2017). "Another strategy was to inhibit JAK2 or STAT3 activation by pretreating lung cancer cells with JAK2 specific inhibitor AG490 (100 μM) or STAT3 specific inhibitor Stattic (7.5 μM) for 24 h, then cultured with CAF-CM." (PMID 29100297, 2017). "The model suggested that JAK2 inhibition in combination with EPO treatment affects lung cancer cells to a much higher extent than erythroid progenitor cells." (PMID 27494133, 2016). "In our study, the regulation of TF by IL-6/JAK2/Stat3 signaling, which participates in metastasis, was also confirmed in lung cancer cells." (PMID 24086497, 2013). "Furthermore, curcumin inhibited JAK2 activity in A549 human lung cancer cell lines, downregulating NF-κB activity and acting on the JAK2/STAT3 signalling pathway." (PMID 40427522, 2025). "This suggests that FA may hinder lung cancer cells from growing and spreading by blocking the JAK2/STAT6 immune signaling pathway." (PMID 40487371, 2025). "In lung cancer, JAK2 expression and PD-L1 expression have been shown to be correlated." (PMID 40642092, 2025). "In addition, some studies have indicated that FGF2 regulates angiogenesis through the JAK2/STAT3 signaling pathways in both lung cancer and melanoma." (PMID 39075612, 2024). "Similarly, activation of the JAK2/STAT3 pathway in TAMs promoted lung cancer metastasis, which was attenuated by knockdown or the use of JAK2/STAT3 inhibitors." (PMID 38424624, 2024). "Additionally, JAK2 gene mutations have been identified in LUSC, suggesting an association between JAK2 mutations and lung cancer progression, as well as poor prognosis and drug resistance." (PMID 38894865, 2024). "However, exo-miRNAs promote proangiogenic factor in melanoma and lung cancer via miR-155-5p and by miR-210 via the JAK2/STAT3 signaling pathway, respectively." (PMID 39075612, 2024). "Furthermore, cucurbitacin E and B inhibited the activation of both STAT3 and JAK2 but mildly activated apoptosis and suppressed tumor growth in lung cancer." (PMID 38397437, 2024). "inhibits lung cancer cells by regulating the IL-6-induced JAK2/STAT3 pathway." (PMID 37291549, 2023). "When UA was applied to the cisplatin-resistant cells, levels of the pluripotent stem cell transcription factors were restrained by the inhibition of the Jak2/Stat3 signaling pathway, which reduced the enrichment of tumor stem cells, and in turn, reversed cisplatin resistance in lung cancer cells." (PMID 37089712, 2023). "Nevertheless, whether JAK2/STAT3 signaling regulates anoikis resistance in lung cancer remains unknown." (PMID 35589677, 2022). "Culturing A549 or CL1-5 lung cancer cells with bone marrow mesenchymal stem cells (MSCs) can increase spheroid formation, drug resistance and overexpression of pluripotent markers by activating IL-6/JAK2/STAT3 pathway." (PMID 36591515, 2022). "Similarly, in A549 human lung cancer cell lines, Curcumin downregulated NF-κB activity and acted on the JAK2/STAT3 signaling pathway by suppressing JAK2 activity; thus, Curcumin is a successful therapeutic drug for treating lung cancer." (PMID 36359936, 2022).
lung cancer (continued). "To investigate the molecular mechanisms underlying the function of the TGF-β1/SH2B3 axis in lung cancer, we next determined whether and how TGF-β1 modulated JAK2/STAT3 and SHP2/Grb2/PI3K/AKT signaling." (PMID 35589677, 2022). "The anti-lung cancer activity of curcumin has been reported and curcumin could suppress cell proliferation and induce apoptosis via modulating the JAK2/STAT3 signaling pathway, PI3K/Akt signaling pathway, and Wnt/β-catenin pathway." (PMID 35630767, 2022). "In this study, we hypothesized that TGF-β1/SH2B3 axis participated in lung cancer development by modulating JAK2/STAT3 and SHP2/Grb2 signaling pathways." (PMID 35589677, 2022). "Next, we determined the roles of SH2B3/JAK2 interaction in lung cancer." (PMID 35589677, 2022). "Furthermore, with a specific SH2B3 antibody, we detected JAK2 expression following SH2B3 immunoprecipitation in lung cancer cells." (PMID 35589677, 2022). "Previous studies demonstrated that overexpression of TRIM32 could promote proliferation of lung cancer cells by activating JAK2/STAT3 signaling pathway." (PMID 35756612, 2022). "Interestingly, there have been reports showing that STIP1 can support the growth and spread of lung cancer and melanoma through the JAK2/STAT3 pathway, a finding in accordance with our current preclinical data." (PMID 35269562, 2022). "Therefore, curcumin is a potent suppressor of CSCs in lung cancer and for this purpose, it can inhibit JAK2/STAT3 axis to impair CSC features." (PMID 34769099, 2021). "We hypothesized that the JAK2-STAT pathway plays an important role in developing lung cancer driven by EML4-ALK." (PMID 34090412, 2021). "Furthermore, antrocin suppressed tumorigenesis in lung cancer mouse xenograft in vivo and enhanced tumor inhibitory response upon combinatorial treatment of antrocin and JAK2 inhibitor." (PMID 33494352, 2021). "Based on the findings of the present study, it can be concluded that microRNA-608 may inhibit cell proliferation, migration, and invasion of lung cancer by targeting BRD4 through the JAK2/STAT3 pathway." (PMID 31621555, 2020). "Furthermore, treatment of A549 and NCI-H292 cells with AG490, a JAK2 inhibitor, reduced FGF2 expression, proving that the JAK2/STAT3 pathway is associated with FGF2 modulation in lung cancer cells." (PMID 33121202, 2020). "Our study illustrated that microRNA-608 may restrain the abilities of proliferation, migration, and invasion of lung cancer cells by targeting BRD4 through the JAK2/STAT3 pathway." (PMID 31621555, 2020). "Taken together, these findings suggest a potential role for JAK2 inhibitors in lung cancer in the context of a specific genomic background that could also possibly work in tandem with immune checkpoint inhibition." (PMID 31844068, 2019). "Moreover, PEAK1 upregulation markedly enhanced the activation of extracellular signal-regulated kinase-1/2 (ERK1/2) and Janus kinase-2 (JAK2) signaling in lung cancer cells." (PMID 30038287, 2018). "In addition, MSI-2 stimulates migration and invasion of bladder cancers by activating the JAK2/STAT3 signaling pathway, and indirectly downregulates tight junction–associated claudins to increase lung cancer cell invasion and metastasis." (PMID 29073938, 2017). "TG101209 was also shown to enhance radiotherapy in lung cancer models by inhibiting JAK2 signaling." (PMID 29290986, 2017). "To evaluate the sensitivity of lung cancer cells to pharmacological inhibition of JAK2, we analyzed the GDSC dataset including exome sequencing data, gene expression profiling data, and screening results of 265 cancer drugs in more than 900 cancer cell lines, among them 103 are NSCLC cell lines." (PMID 29082853, 2017). "Among the 90 CCLE cancer cell lines with JAK2 homozygous deletion, 17 were lung cancer cell lines." (PMID 28977839, 2017).
lung cancer (continued). "In a series of biochemical and genetic studies, we clearly showed that Jak2/Stat3 pathway, together with other well characterized IL-6 downstream signal pathways, regulates the autocrine production of IL-6 in lung cancer cells and various drug resistant cancer cells." (PMID 21122157, 2010). "Furthermore, erianin also downregulated the protein expression levels of p-STAT3, p-JAK2, MMP-2, MMP-9, COX-2, HIF-1α, and IL-6, indicating that erianin inhibited angiogenesis of lung cancer cells by targeting JAK2/STAT3 pathway and inhibiting IDO-induced angiogenesis." (PMID 37608888, 2023). "Mesenchymal stem cells could conduce to tumor formation by IL-6/JAK2/STAT3 pathway in lung cancer." (PMID 37716993, 2023). "Hence, as a potential antitumor drug, UA may be able to inhibit the enrichment of the lung CSC population by inhibiting the activation of the Jak2-Stat3 pathway and preventing the resistance of lung cancer cells to cisplatin." (PMID 37089712, 2023). "In this study, the potential targets of Pinellia ternata highly overlap with lung cancer pathological genes, with FGFR4, CDK2, JAK2, KDR, PAK4, PTK2 and PDGFRA being the core." (PMID 42149884, 2026). "In lung cancer, TM4SF4 expression is upregulated where it promotes tumor growth, migration, and invasion through activation of PI3K/AKT and JAK2/STAT3 pathways, as well as preserving cancer stem cell features." (PMID 39999090, 2025). "Oxymatrine (OMT), the oxide derivative of MT, inhibited tumor growth in a lung cancer xenograft model by blocking JAK1, JAK2 and Src kinase activation upstream of STAT5, thereby suppressing STAT5 phosphorylation." (PMID 40841966, 2025). "It caused S-phase arrest, suppressed cell migration, and inhibited the JAK2/STAT3 (Janus kinase 2/signal transducer and activator of transcription 3) signaling pathway, suggesting its role as a lung cancer therapeutic agent." (PMID 40149610, 2025). "MYC downregulates H3K27 acetylation and JAK2 expression, impairing the IFN-γ signaling pathway and rendering lung cancer cells resistant to PD1/PD-L1 therapy." (PMID 40166469, 2025). "The Western blotting results revealed that, compared with the control group, the BMSC, QSFZYL, IFN-γ + BMSC + QSFZYL, and IFN-γ-BMSCs groups exhibited reduced PD-L1, JAK2, STAT3, and p-STAT3 expression in lung cancer tissues." (PMID 40642092, 2025). "Compared to the control group, JAK2, STAT3, and PD-L1 protein expression was reduced in lung cancer tissues of mice from the BMSCs, QSFZYL, IFN-γ + BMSCs, and IFN-γ + BMSCs + QSFZYL groups." (PMID 40642092, 2025). "Activation of LPAR1 induces Janus kinase 2 (JAK2) and signal transducer and activator of transcription 3 (STAT3) signalling to promote lung cancer cell migration." (PMID 38607068, 2024). "IL-6 secreted by TAMs promotes lung cancer progression and metastasis in vivo and in vitro by activating the EMT pathway, which can be attenuated by the use of JAK2/STAT3 pathway inhibitors or IL-6 monoclonal antibodies." (PMID 38424624, 2024). "The CHRNA5 promoter harbours a binding site for STAT3, and nicotine induces the proliferation of lung cancer cells by enhancing CHRNA5 expression and activating the JAK2/STAT3 signalling cascade." (PMID 38879667, 2024). "LDOC1 interacts with Ligand-of-Numb protein X1 (LNX1), an E3 ligase, to induce Janus kinase 2 (JAK2) ubiquitination and degradation, which negatively regulates STAT3 activation and IL-6 secretion in lung cancer cells." (PMID 39682774, 2024). "Following radiation to lung cancers, PAK1 can be phosphorylated by JAK2 at critical residues of tyrosine, instead of serine/threonine, to maintain protein stability and enhance nuclear translocation." (PMID 37564209, 2023). "SH2B3 interacts with Janus kinase 2 (JAK2) and Src homology region 2-containing protein tyrosine phosphatase 2 to inhibit JAK2/STAT3 and PI3K/AKT signaling pathway-mediated anoikis in lung cancer." (PMID 36230714, 2022).
lung cancer (continued). "It has been reported that several oncogenic tyrosine kinases phosphorylated LDHA at Y10 in various cancers, such as FGFR1 in lung cancer, BCR-Abl in chronic myelogenous leukemia, and JAK2 in human erythroleukemia." (PMID 35525866, 2022). "TGF-β and IL-6/JAK2/STAT3 signal pathway form a positive feedback signal loop, mediating the interaction between MFs and lung cancer cells." (PMID 36591515, 2022). "Although most solid tumors do not have JAK2 mutations, more and more evidence shows that abnormal JAK2 signaling acts importantly in solid tumors such as CRC, BC, GC, lung cancer and prostate cancer." (PMID 36591515, 2022). "TGF-β and IL-6/JAK2/STAT3 pathway form a positive feedback signal loop, mediating the interaction between MFs and lung cancer cells." (PMID 36591515, 2022). "CAFs isolated from lung cancer tissue promote metastasis by secreting IL-6, which activates JAK2 and STAT3 signaling and also induces EMT via increasing vimentin expression in lung cancer cells both in vitro and in vivo." (PMID 36620544, 2022). "Here, we evaluated the expression of NF-κB, AICDA, Akt, IL-6, Jak2, and Stat3 by EGFR-TKI-resistant lung adenocarcinoma (LAC), and found that NF-κB and AICDA are major players in the acquired resistance of lung cancer to TKIs." (PMID 35740609, 2022). "It was reported that several oncogenic tyrosine kinases phosphorylated LDHA at Y10 in various cancers, such as FGFR1 in lung cancer, BCR-Abl in chronic myelogenous leukemia, and JAK2 in human erythroleukemia." (PMID 35525866, 2022). "The mechanisms regarding IL‐17A in PF, inflammation, or lung cancer include a variety of signalling pathways, such as TGF‐β, PD‐1/STAT3, JAK2, and NF‐κB signalling." (PMID 36308405, 2022). "Aberrant activation of Janus kinase 2 (JAK2)/signal transducer and activator of transcription 3 (STAT3) signaling has been reported in the progression of numerous cancers including lung cancer." (PMID 35589677, 2022). "Chen found that Huaier inhibited lung cancer proliferation and metastasis through MTDH, JAK2/STAT3, and MAPK." (PMID 35470770, 2022). "Our results suggest that the JAK2-STAT signaling pathway plays an important role in the occurrence and development of lung cancer mediated by EML4-ALK." (PMID 34090412, 2021). "In lung cancer cells, enforced PEAK1 expression induces EMT via activating extracellular signal-regulated kinase-1/2 (ERK1/2) and Janus kinase-2 (JAK2) signaling." (PMID 34365903, 2021). "Immunohistochemistry analyzed the cellular localization of p-STAT6, p-JAK2, and ALK in EML4-ALK-positive lung cancer tissues." (PMID 34090412, 2021). "We observed that Hiltonol+++ (Hiltonol in combination with inhibitors of IL6, JAK2, STAT3) significantly suppressed the viability of lung cancer cells compared to Hiltonol alone." (PMID 33562773, 2021). "In addition, it could interact with the TGF-β and JAK2/STAT3 pathway in lung cancer." (PMID 32802874, 2020). "Huaier Granule extract suppresses proliferation and metastasis in lung cancer cells by downregulating the MTDH, JAK2/STAT3, and MAPK signalling pathways." (PMID 32244796, 2020). "In this study, A549 lung carcinoma cells exposed to PM10 showed increases of IL-6 and phosphorylation of JAK1/JAK2/STAT3 signaling molecules." (PMID 33374928, 2020). "Our results reveal that MVP inhibited lung cancer growth by suppression of STAT3 signal pathway, which is regulated by JAK2 and RAF-MEK-ERK pathways." (PMID 31092229, 2019). "This study highlighted that LDOC1 acts as a novel native negative regulator of JAK2 and STAT3 in lung cancer." (PMID 30634502, 2019). "Overall, our results elucidated a crucial role of LDOC1 in lung cancer and revealed how LDOC1 acts as a bridge between tobacco exposure and the IL-6/JAK2/STAT3 loop in this human malignancy." (PMID 30634502, 2019).
lung cancer (continued). "In this study, we show that PEAK1 overexpression promotes lung cancer metastasis, EMT and EMT-related traits through regulating ERK1/2 and Janus kinase-2 (JAK2) signaling." (PMID 30038287, 2018). "Our findings reveal that PEAK1 overexpression contributes to activation of the ERK1/2 and JAK2 pathways and promotes EMT in a lung cancer subset." (PMID 30038287, 2018). "In addition, PD98059 and/or AZD1480 can reduce the PEAK1-enhanced migration, invasion and EMT of NSCLC cells, suggesting that targeting the ERK1/2 and JAK2 pathways could potentially be used to treat PEAK1-overexpressing lung cancer in combination with standard chemotherapy." (PMID 30038287, 2018). "Our study demontrated that the TGF-β and IL-6/JAK2/STAT3 signaling pathways form a positive feedback signaling loop that mediated the interactions between MFs and lung cancer cells." (PMID 28819126, 2017). "Our data supports that polyI:C (its analogue, Hiltonol) is a promising adjuvant in combination with anti-IL6 antibody and/or JAK2/STAT3 inhibitors, for lung cancer immunotherapy." (PMID 28427199, 2017). "When cultured with CAF-CM, both p-JAK2 and p-STAT3 expression in lung cancer cells were increased, and total STAT3 expression remained unchanged." (PMID 29100297, 2017). "Blockade of JAK2/STAT3 and TGF-β signaling by specific inhibitors significantly inhibited cell proliferation in vitro and tumor growth in vivo of lung cancer cells." (PMID 28819126, 2017). "Treatment with SB-431542 (10 μM), JSI-124 (0.2 μM), or SB-431542 (5 μM) + JSI-124 (0.1 μM) inhibited the expression of JAK2, STAT3, survivin and c-myc in lung cancer cells in normal medium and MF-CM, based on RT-PCR measurements and by Western Blots." (PMID 28819126, 2017). "Notably, JAK2, STAT3, and PD-L1 protein expression was significantly lower in lung cancer tissues of mice in the IFN-γ + BMSCs + QSFZYL group compared to the BMSCs, QSFZYL, and IFN-γ + BMSCs groups (P< 0.05)." (PMID 40642092, 2025). "Notably, JAK2 activation modulates STAT3 phosphorylation, it has been shown that nicotine interacts with cell surface α5-nAChR to activate various signaling pathways, including the JAK2/STAT3 pathway, thereby affecting lung cancer progression." (PMID 40143965, 2025). "By stimulating the JAK2/STAT3-C/EBPβ-IL6 pathway, IL-6 can promote the release of additional IL-6, creating a positive feedback loop in TAMs; thus, it promotes EMT, invasion, and migration of lung cancer in vivo and in vitro." (PMID 38424624, 2024). "Similarly, earlier research has shown that berberine hinders lung cancer cell growth by affecting the matrix metalloproteinase 2 (MMP-2)/Bcl-2/Bax and Janus kinase 2 (Jak2)/vascular endothelial growth factor (VEGF)/NF-κB/AP-1 signaling pathways." (PMID 38334679, 2024). "JAK2/STAT3 signaling pathway is widely demonstrated to highly abnormally activate in various cancers, for example, pancreatic cancer, gastric cancer, breast cancer, liver cancer, colorectal cancer, colon cancer, ovarian cancer, lung cancer." (PMID 37716993, 2023). "Our studies also suggested the inhibition of IL-6/JAK2/STAT3 signal transduction by the exogenous rhTβ4 maybe part of reason for its inhibitory effect on IPF and lung cancer." (PMID 36835236, 2023). "In addition, Zhang colleagues found that ginseng Rh4 inhibited the expression of JAK2, STAT3, and p-STAT3, which inhibited the growth and metastasis of lung cancer." (PMID 38202610, 2023). "In addition, the results of Western blots showed that phosphorylation of JAK2 and STAT3 protein was inhibited by the treatment of exogenous rhTβ4 in both a lung cancer cell line and a lung fibroblasts cell line in vitro." (PMID 36835236, 2023). "This JAK2-mediated PAK1 tyrosyl phosphorylation strengthens the transcriptional repression activity of snail to mediate epithelial-mesenchymal transition and radioresistance, while PAK1Y3F mutant nullifies these effects in irradiated lung cancers." (PMID 37564209, 2023).